RELB (RELB proto-oncogene, NF-kB subunit)
Diseases named in the same sentence as RELB in open-access papers (continued):
Sharing a sentence is not in itself a finding about the gene and the disease.
glioma (continued). "A main molecular hallmark of epithelial-to-mesenchymal transition (EMT) is a switch in expression from E-cadherin to N-cadherin; thus, these data are consistent with a role for RelB in promoting EMT to control a mesenchymal phenotype in glioma." (PMID 23451236, 2013). "To validate the role of RelB in the tumorigenic potential of glioma cells in vivo, we assayed tumor growth in subcutaneous and intracranial mouse xenografts using fluorescently labeled tumor cells." (PMID 23451236, 2013). "Together, these results demonstrate that RelB expression strongly correlates with glioma invasion and migration in 3D matrices." (PMID 23451236, 2013). "It has been reported that the NF-κB transcription factor, RelB, is highly expressed in mesenchymal glioma, compared with the classical, neural and pro-neural glioma subtypes." (PMID 23451236, 2013). "We have identified the NF-κB RelB protein as a strong oncogenic driver of the mesenchymal subtype of glioma and demonstrated that RelB promotes glioma cell survival, proliferation and invasiveness in vitro and in vivo." (PMID 23451236, 2013). "To assess a role for RelB in glioma cell motility, we employed an in vitro scratch assay using U87 cells grown in serum-containing medium to promote growth as adherent monolayers." (PMID 23451236, 2013). "The proposed role for RelB in laryngeal cancer is in line with other mechanistic studies that indicate it to be a promoter of oncogenic transcription and stemness in tumor initiating cells of colon cancers, gliomas, lymphomas, and myelomas." (PMID 29371965, 2017). "Notably, we observed that similar to BT116 cells, TWEAK was also able to promote invasion in BT114 glioma cells, which are minimally invasive and express low levels of RelB." (PMID 25622756, 2015). "Notably, the ability of TWEAK to induce NIK expression and promote invasion is not only observed in glioma cells expressing high levels of RelB, but also in glioma cells with low levels of endogenous RelB expression." (PMID 25622756, 2015). "In glioma cells that display elevated noncanonical NF-κB signaling, loss of RelB attenuates invasion without affecting RelA expression or phosphorylation and RelB is sufficient to promote invasion in the absence of RelA." (PMID 25622756, 2015). "Additionally, RelB regulates expression of Olig2, a regulator of cancer stem cell proliferation and a candidate marker for the cell of origin in glioma." (PMID 23451236, 2013). "We first evaluated RelB expression levels in two well established glioma cell lines, U87 and U373." (PMID 23451236, 2013). "In this study, we investigate the role of RelB in glioma tumorigenesis and pathogenesis." (PMID 23451236, 2013). "Thus far, our data demonstrate that RelB is an oncogenic driver for mesenchymal glioma in vitro and in vivo." (PMID 23451236, 2013). "Interestingly, in glioblastoma multiforme (GBM) the NF-κB family member RelB was shown to interact with YY1 and promote expression of GBM specific genes as well as pro-inflammatory cytokines leading to infiltration of glioma associated macrophages and thus tumor progression." (PMID 31824839, 2019). "Importantly, RelB promotes the expression of mesenchymal genes in glioma cells." (PMID 28598356, 2017). "Furthermore, RelB knockdown strongly reduces glioma cell migration and invasion." (PMID 27153093, 2016). "RelB knockdown cells displayed diminished RNA expression of the mesenchymal genes N-Cadherin/CDH2, SMAD2 and TGFβ3, as well as lower levels of YKL-40/CHI3L1, a biomarker of aggressive and recurrent gliomas that is very strongly associated with the mesenchymal glioma subtype." (PMID 23451236, 2013). "However, the expression of RelB in neural precursor cells during mammalian development is consistent with the possibility that increased RelB activity may be involved in CNS cancers." (PMID 23451236, 2013).
glioma (continued). "In contrast to RelA, RelB protein levels were more varied in the different glioma lines, and high RelB-expressing cells (U87, BT25, and BT116) invaded much more efficiently than low RelB-expressing cells (BT132, BT114 and U373)." (PMID 25622756, 2015). "We find that RelB promotes the expression of mesenchymal genes including YKL-40, a marker of the MES glioma subtype." (PMID 23451236, 2013). "Mangiferin was verified to inhibit activation of the noncanonical NF-κB pathway by TWEAK treatment in glioma cells, as seen with a reduction in p100-p52 processing and RelB." (PMID 36945490, 2023). "Analysis of patients data from the Cancer Genome Atlas (TCGA) and the Chinese Glioma Genome Atlas (CGGA) indicates that increased RelB expression correlates with more severe glioma grade, shorter life expectancy, and overall negative prognosis." (PMID 34198987, 2021). "RelB can promote invasion in glioma cells without affecting the activity of RelA and the classical NF-κB signaling." (PMID 30473630, 2018). "We have recently shown that noncanonical NF-κB/RelB signaling is a potent driver of tumorigenesis and invasion in the aggressive, mesenchymal subtype of glioma." (PMID 25622756, 2015). "Our data thus far demonstrate that a low concentration of TWEAK promotes invasion and predominantly activates noncanonical NF-κB signaling in glioma tumor lines with high RelB expression." (PMID 25622756, 2015). "Oncogenic roles for RelB have been described, but the functions of RelB in gliomas, or other cancers of the CNS, have not been previously examined." (PMID 23451236, 2013). "RelB controls EMT and the expression of the mesenchymal genes in glioma, including YKL-40/CHI3L1, a secreted glycoprotein that is a prognostic indicator for poor survival in high-grade glioma as well as other cancers and inflammatory diseases." (PMID 23451236, 2013). "However, a functional role for RelB in gliomas has not been established." (PMID 23451236, 2013). "Specifically, we demonstrate that RelB promotes glioma invasion in the absence of RelA, and that TWEAK preferentially regulates noncanonical NF-κB signaling in glioma through a novel, signal-specific induction of NIK expression." (PMID 25622756, 2015). "In this study, we investigate the effects of TWEAK on noncanonical NF-κB/RelB signaling, MMP9 expression and glioma invasion." (PMID 25622756, 2015). "It has been proposed that glioma CSCs express differentiation markers similar to those in normal glia and neurons, such as of oligodendrocytes (ASCL1, OLIG2 and DLL3), astrocytes (GFAP), neurons (β-tubulin III, SYT1 and SLC12A5), and markers of inflamed astroglial cells (SERPINE1, TGFB1 and RELB)." (PMID 31661894, 2019).
multiple myeloma (16 papers, 2013 to 2023). "Myeloma cells additionally acquire gain-of-function mutations in the non-canonical NFκB module, which induces partial proteolysis of p100 into p52 to promote RelB:p52/NFκB activation from p100-inhibited complex during immune cell differentiation." (PMID 27641334, 2017). "Moreover, it remains unclear if the myeloma-associated RelB only activates the expression of RelA-target pro-survival genes or also mediates the expression of genes that are normally not induced by RelA." (PMID 29772694, 2018). "RelB:p50 is necessary and sufficient to provide pro-survival and anti-apoptotic signals in multiple myeloma." (PMID 38169968, 2023). "Another study identified that tumor-promoting cytokines, such as tumor necrosis factor, activates RelB:p50 in multiple myeloma cell line." (PMID 38169968, 2023). "This study found that G9a interacts with NF-κB pathway as a key regulator of RelB in multiple myeloma and regulates RelB-dependent multiple myeloma survival." (PMID 32477831, 2020). "In contrast to its rather limited physiological functions, RelB was reported to play a critical role in promoting survival and drug resistance of myeloma cells." (PMID 29772694, 2018). "Further mechanistic investigations are warranted to unravel if RelB indeed functions as an activator and a repressor in different subsets of myeloma cells." (PMID 29772694, 2018). "In particular, NIK-dependent non-canonical signaling amplifies RelA NF-κB responses and canonical signaling reinforces RelB NF-κB activity in myeloma cells." (PMID 29772694, 2018). "It was shown that physical interaction of myeloma cells with the extracellular matrix (ECM) component fibronectin per se induces a RelB-dependent, pro-survival NF-κB signaling in cancerous cells." (PMID 29772694, 2018). "Remarkably, NF-κB dependent RelB synthesis perpetuated a sustained RelB:p50 activity upon TNF stimulation of these myeloma cells." (PMID 29772694, 2018). "In sum, we provide evidence that cancer-associated mutations perpetuate TNF-induced pro-survival NFκB response through autoregulatory RelB control and thereby exacerbate environmental drug resistance in multiple myeloma." (PMID 27641334, 2017). "In sum, we provide evidence that cancer-associated mutations perpetuate TNF-induced pro-survival NFκB activity through autoregulatory RelB control and thereby exacerbate environmental drug resistance in multiple myeloma." (PMID 27641334, 2017). "Genetic analyses and mathematical modeling studies substantiated that depletion of p100 in myeloma cells triggers this autoregulatory loop to promote perpetuating RelB:p50/NFκB response to TNF." (PMID 27641334, 2017). "Taken together, p100 depletion reinforced pro-survival TNF response in multiple myeloma by prolonging classical NFκB function via the autoregulatory RelB pathway." (PMID 27641334, 2017). "A frequent constitutive RelB DNA-binding activity was reported in a cohort of newly diagnosed multiple myeloma patients." (PMID 27153093, 2016). "It was demonstrated that RelB plays a crucial role in promoting multiple myeloma cell survival via the increased expression of a subset of anti-apoptotic NF-κB target genes (e.g., cIAP2) by a direct transcriptional control." (PMID 27153093, 2016). "These p100-depleted myeloma cells also possessed constitutive RelB activity." (PMID 31134075, 2019). "Furthermore, in multiple myeloma, it is well known that RelB is able to exert a crucial anti-apoptotic role in malignant cells." (PMID 31586084, 2019). "Furthermore, chronic TNF treatment of these p100-depleted myeloma cells induced RelA:p50 as well as RelB:p50 complexes, both of which activated the expression of pro-survival factors." (PMID 31134075, 2019). "Our current study indicated that p100 depletion might enable RelB-dependent, late-acting expressions of pro-survival genes in myeloma cells subjected to brief TNF stimulation." (PMID 31134075, 2019).
multiple myeloma (continued). "It remains unclear if CD40-activated non-canonical signaling degrades p100 completely to promote canonical RelB:p50 activation, or crosstalk between CD40-induced NF-κB pathways contributes to aberrant RelB:p52 activation myeloma cells." (PMID 29772694, 2018). "RelB is also a crucial positive regulator of cell survival in multiple myeloma (MM)." (PMID 29983639, 2018). "Finally, our database analyses indicate a possible role of autoregulatory RelB/NFκB pathway in resistance of myeloma patients from therapeutic intervention." (PMID 27641334, 2017). "Indeed, high RelB mRNA expressions in myeloma patients correlated with the augmented level of pro-survival factors and resistance to therapeutic intervention." (PMID 27641334, 2017). "Rather autoregulatory RelB control mediated precarious collaboration between widespread cell-intrinsic mutations in the non-canonical NFκB module and dynamical signaling induced by TNF in multiple myeloma." (PMID 27641334, 2017). "Furthermore, these results extended the possibility that TNF-induced RelB:p50 activity provides for the pro-survival NFκB transcription function in p100-depleted myeloma cells." (PMID 27641334, 2017). "Intriguingly, pro-survival TNF response is attributed to RelB:p50, and not RelA:p50, NFκB activity in myeloma cells harboring non-canonical mutations." (PMID 27641334, 2017). "More so, autoregulatory RelB synthesis prolonged this TNF-induced RelB:p50 activity in myeloma cells harboring non-canonical mutations." (PMID 27641334, 2017). "RelA- and RelB-DNA binding activity in CD138+ cells from newly diagnosed multiple myeloma patients." (PMID 23555623, 2013). "Thus, it is likely that the prosurvival effects of RelB observed in multiple myeloma might be generalized to other B-cell neoplasms, especially those addicted to NF-κB." (PMID 27153093, 2016). "Nevertheless, not only mutations onto the non-canonical NF-κB module are prevalent in MM, but RelB NF-κB dimers also appear to supplement pathological RelA functions in myeloma cells." (PMID 29772694, 2018). "Despite the role of CD40 in the pathogenesis of the disease, CD40-mediated regulation of the RelB NF-κB activity has not been investigated in the context of multiple myeloma." (PMID 29772694, 2018). "Finally, myeloma cells lacking p100 owing to genetic aberrations produced a long-lasting pro-survival RelB response to brief TNF stimulation." (PMID 31134075, 2019). "Interestingly, a lack of p100 in myeloma cells, attributed to genetic aberrations, provokes an alternate RelB:p50 NF-κB response via the canonical pathway." (PMID 31554891, 2019). "Finally, non-canonical signaling in BMSCs produce the RelB-target homeostatic chemokine SDF1α, which directs homing of myeloma cells to the bone marrow niche." (PMID 29772694, 2018).
lung carcinoma (13 papers, 2012 to 2024). "Increased β3, by interacting with galectin-3, thus activating KRAS, RELB, and NF-ΚB pathways, is involved in erlotinib and lapatinib resistance in lung cancer and linsitinib resistance in pancreatic cancer." (PMID 39063187, 2024). "It would also be interesting to test the role of RelB and c-Rel in lung cancer, particularly given the fact that p100 is the main inhibitor and p52 is the main functional partner of RelB." (PMID 38385745, 2024). "Noncanonical NF‐κB signaling and Wnt/β‐catenin signaling regulate lung cancer progression via RELB proto‐oncogene (RELB) and β‐catenin, respectively." (PMID 39429877, 2024). "In the case of ER-positive breast carcinoma, higher expression of RelB is associated with decreased relapse-free survival (RFS) and overall survival (OS) rate, whereas in other tumours, such as lung carcinoma, enhanced expression of NIK and RelB is associated with enhanced metastasis and shorter OS." (PMID 36899924, 2023). "In SPC-A1 lung cancer cells, cell proliferation is suppressed by the RelB-silencing." (PMID 30473630, 2018). "It was evident that the level of RelB protein was higher in LIHC, GBM, HNSC, PAAD, clear cell renal carcinoma and lung cancer, which was consistent with the corresponding mRNA expression in these cancer types." (PMID 37388242, 2023). "The increased expression of the β3 integrin has been implicated in drug resistance, including resistance to erlotinib and lapatinib in lung cancer and to linsitinib in pancreatic cancer, through interactions with galectin-3 and the activation of KRAS, RELB, and the NF-ΚB pathway." (PMID 39201327, 2024). "Data from Gene Expression Profiling Interactive Analysis (GEPIA) 25 analysis confirmed a significantly positive correlation of MARCKS expression with TNFR, RELA, BCL2A1, CXCL1, RELB or TNF-alpha in lung cancer samples but not in normal lung tissues." (PMID 33754052, 2021).
autoimmune disease (11 papers, 2018 to 2025). A disorder resulting from loss of function or tissue destruction of an organ or multiple organs, arising from humoral or cellular immune responses of the individual to their own tissue constituents. "Our results support a model in which RelB competes with RelA for κB sites, and thus RelB functions to dampen the expression of immune response genes in DCs and reduces the risk for auto-inflammatory and autoimmune disease." (PMID 39929805, 2025). "The RELB protein, primarily involved in the non-canonical activation of the NF-κB pathway, is important for Treg differentiation and function, with RELB defects being associated with autoimmune disorders." (PMID 38786036, 2024). "This conclusion has important implications for autoimmune diseases where polymorphisms in genes such as Traf6, Relb, and Rel reduce expression and transcriptional activity of RelB in thymus, including loss of function." (PMID 29872433, 2018). "However, RelB-deficient mice have reduced lifespan due to multiorgan autoimmune disease and severe thymic medullary atrophy which limits interpretation of effects of RelB on mTEC differentiation or function." (PMID 29872433, 2018). "RELA and RELB are key TFs of the NFκB pathway, and their reduced expression leads to dysregulation of the NFκB pathway, resulting in severe autoimmune diseases and reduced immunity." (PMID 38192721, 2023). "Currently, RelB-silenced tolerogenic DCs are used to study autoimmune diseases, such as systemic lupus erythematosus and myasthenia gravis." (PMID 31881915, 2019). "Organ-specific autoimmune disease in these mice developed much later than in RelB−/− mice, as peripheral tolerance and pTreg function was shown to be normal." (PMID 29872433, 2018). "To address this, we studied mTECs and dendritic cells (DCs), which critically regulate negative selection, and thymic regulatory T-cells (tTreg) in RelB−/− mice, which have spontaneous multiorgan autoimmune disease." (PMID 29872433, 2018). "The reduced thymic medullary area for negative selection and Treg development, and the reduction in mTEC AIRE are together likely to explain the organ-specific autoimmune disease in RelB−/− mice." (PMID 29872433, 2018). "The increased severity of autoimmune disease in RelB−/− relative to AIRE−/− mice is also consistent with the additional Treg dysfunction in RelB−/− mice." (PMID 29872433, 2018). "Also, CCR7+/RELB+/IRF1+ T cells had been revealed as an independent responsor in JIA among other types of autoimmune diseases, severing as potential therapeutic target." (PMID 40406113, 2025). "This second pathway plays a critical role in regulating immune homeostasis, and its dysregulation contributes to inflammatory and autoimmune diseases suggesting that RelB may act as a repressor of NF-κB-responsive gene expression." (PMID 32582184, 2020). "The RelB-associated non-canonical pathway plays a critical role in regulating immune homeostasis, and its dysregulation contributes to inflammatory and autoimmune diseases." (PMID 31881915, 2019). "However, the severe thymic medullary atrophy and multiorgan autoimmune disease in RelB−/− mice limits interpretation of effects of RelB on tTreg development." (PMID 29872433, 2018). "Furthermore, adoptive transfer of low numbers of RelB-sufficient DCs to RelB−/− mice induced dominant Treg-mediated suppression of autoimmune disease, as measured by weight gain, improved clinical scores, and reduced granulocyte infiltration of the spleen." (PMID 29872433, 2018). "Thus, the medullary niche for mTEC, DC, and tTreg survival and expansion can be preserved in RelB−/− thymus either by depletion of granulocytes or suppression of autoimmune disease using DC immunotherapy." (PMID 29872433, 2018). "Therefore, we examined whether thymic medullary atrophy in RelB−/− mice could be prevented by adoptive transfer of DCs, through dominant tolerance of autoimmune disease." (PMID 29872433, 2018).